MTOR (mechanistic target of rapamycin kinase)
Diseases named in the same sentence as MTOR in open-access papers (continued):
Sharing a sentence is not in itself a finding about the gene and the disease.
osteosarcoma (continued). "Targeting MTOR and NFKB pathways may potentially induce tumor cell death and improve Anoikis in osteosarcoma, thus positively influencing patient prognoses." (PMID 37980450, 2023). "In osteosarcoma, TRIM22 can interact with Nrf2 and accelerate its degradation by inducing ubiquitination dependent on its E3 ligase activity, thus activating downstream AMPK/mTOR signaling, and affecting Nrf2-mediated ROS imbalance." (PMID 36261847, 2022). "Thus, ginsenoside Rh2 exerts anticancer effects in osteosarcoma through influencing the activity of MAPK, PI3K/AKT/mTOR, and NF‐кB pathways." (PMID 35220526, 2022). "As the data suggest, inhibition of the mTOR pathway has been expected as a promising therapeutic approach, but mTOR inhibitors have not proved their efficacy in osteosarcoma treatment, only in combination with different cytotoxic agents." (PMID 35392503, 2022). "Thus, we can conclude that STEAP2 acts as an oncogene in osteosarcoma progression, while EFEMP2 enables PI3K/AKT/mTOR axis initiation and EMT by partly targeting STEAP2, thereby facilitating osteosarcoma cell infiltration and migration." (PMID 36316642, 2022). "Moreover, N’-[(3Z)-1-(1-hexyl)-2-oxo-1,2-dihydro-3H-indol-3-ylidene] benzohydrazide (MDA19) was found to downregulate the expression of the main proteins involved in the EMT process, specifically PI3K/AKT/mTOR, inhibiting EMT in osteosarcoma cells." (PMID 36591458, 2022). "Based on these experimental results, we hypothesize that osteosarcoma cells secrete excessive EFEMP2, which in turn targets STEAP2 initiating the PI3K/Akt/mTOR axis and inducing EMT which in turn enhances osteosarcoma cell infiltration and migration." (PMID 36316642, 2022). "The implications of NCT-503 sensitization to non-rapalog mTORC1 inhibition offer a solution to previous negative clinical trials using mTOR inhibitors in osteosarcoma." (PMID 33503424, 2021). "Numerous studies have shown that pristimerin inhibits PI3K/AKT pathway evidenced by the dephosphorylation of Akt and its downstream factors such as mTOR, FoxO3a, and NF−κB in UM, OSCC, breast cancer, pancreatic cancer, ovarian cancer, osteosarcoma, and fibrosarcoma." (PMID 34026649, 2021). "Further results showed that overexpression of Notch1 could inhibit osteosarcoma cell proliferation and improve apoptosis and autophagy by regulating the PI3K/Akt/mTOR pathway." (PMID 34495871, 2021). "On this basis, we applied methods to induce autophagy in osteosarcoma cells, inhibit the autophagy process of osteosarcoma cells, and inhibit the phosphorylation level of mTOR by rapamycin to clarify the relationships among aloin, autophagy, the PI3K/AKT/mTOR axis and apoptosis." (PMID 34819120, 2021). "We used the human osteosarcoma cell line U2OS and its CRISPR/Cas9-generated NRF2-knockout counterpart to test the requirement for NRF2 and the involvement of mTOR regulators in the SFN-mediated inhibition of mTOR." (PMID 31409554, 2021). "A monoclonal antibody against IGF-1R (R1507) was able to restrict growth in osteosarcoma xenograft tumours alone and in the presence of the mTOR inhibitor rapamycin, but did not have a clinical effect in a phase II clinical trial." (PMID 32961800, 2020). "Curcumin is known to induce autophagy by inhibiting the Akt/mTOR pathway and activating the ERK1/2 pathway in human malignant glioma cells, and by upregulating the c-Jun N-terminal kinases (JNK) pathway in human osteosarcoma cells." (PMID 30004453, 2018). "We provided further evidence that TSSC3 overexpression induces autophagy, likely via the Src-mediated PI3K/Akt/mTOR pathway, and autophagy, at least partially, contributes to TSSC3-induced tumorigenesis and metastasis suppression in osteosarcoma, both in vitro and in vivo." (PMID 30092789, 2018).
osteosarcoma (continued). "For example, it activates endophilin-mediated Jun-N-terminal kinase in human embryonic kidney 293 cells, mTOR signaling to modulate HeLa cell growth and viability, and post-transcriptionally regulates BH3-only proteins to regulate cell death in human osteosarcoma cells." (PMID 27343552, 2016). "Given the paucity of active agents available for the treatment of recurrent and refractory osteosarcoma, inhibition of PI3K and mTOR may present a viable treatment strategy deserving of clinical investigation." (PMID 27441088, 2016). "Our research demonstrated that miR-199a-3p and miR-34a could down-regulate its target genes, mTOR, MET and MDM4 in human osteosarcoma cells." (PMID 24957404, 2014). "Studies done in preparation for this trial showed that components of the mTOR pathway, mTOR, p-S6, p-4EBP1 are expressed in canine osteosarcoma cell lines and primary tumors (data not shown)." (PMID 20543980, 2010). "Therefore, our assayal results suggest that TRIM17 regulates the expression of PDK1 through FTO-mediated m6A demethylation in osteosarcoma, and further activates downstream AKT/mTOR signaling pathway activity to positively regulate the malignancy of osteosarcoma." (PMID 41145484, 2025). "Arbutin inhibits osteosarcoma cell proliferation, migration, and invasion via miR-338-3pl MTHFD1L (methylenetetrahydrofolate dehydrogenase (NADP+ Dependent) 1 Like) and by inactivating the AKT (protein kinase B)/mTOR (mammalian target of rapamycin) signaling pathway." (PMID 38958363, 2024). "Furthermore, its capacity to block Akt-mTOR activation significantly hindered the growth of osteosarcoma xenografts in nude mice, indicating the potential therapeutic value of concurrent mTORC1/2 inhibition with XL388 in osteosarcoma treatment." (PMID 39015499, 2024). "Several studies have found abnormal expression of the Akt/mTOR signaling pathway in osteosarcoma, but it is not known whether it is involved in the effect of PRKCI on osteosarcoma." (PMID 39015499, 2024). "Expression levels of p-AKT and p-mTOR were increased upon ATP5A1 upregulation, and importantly, the inhibition of phosphorylation levels of biomarkers within the mTOR pathway in HSPD1 knockdown osteosarcoma cells was partially reversed by exogenous expression of ATP5A1." (PMID 39430254, 2024). "Additionally, different signaling pathways such as STAT3/c‐Myc signal pathway, JNK signl pathway, PI3k/AKT/mTOR signal pathway, WNT/β‐catenin signal pathway, and RhoA signal pathway can influence the development of osteosarcoma by regulating PCD in osteosarcoma cell." (PMID 38800967, 2024). "This exact effect has been obtained in a study in osteosarcoma in which this compound induced autophagy and apoptosis through the PI3K/Akt/mTOR pathway, suggesting that this molecule may be a useful drug for inhibiting metastasis linked to autophagy in both cancer types." (PMID 36983973, 2023). "Therefore, we speculate that SOX21-AS1 can regulate the expression of mTOR and KLF4 through sponging hsa-mir-7-5p and hsa-mir-145-5p, thereby regulating the proliferation of osteosarcoma." (PMID 34696664, 2022). "Treatment with an anti-IGF1R antibody in mouse xenografts of osteosarcoma showed promising results, and this preclinical evaluation provided motivation for a phase II clinical trial testing an anti-IGF1R antibody in combination with mTOR inhibitor in several sarcomas." (PMID 35887382, 2022). "However, our non-significant results are in contrast with those expected if LAT2 led to mTORC1 phosphorylation suggesting no LAT2-mediated mTOR phosphorylation in tissue of osteosarcoma patients." (PMID 36438828, 2022). "Thus, PI3K/Akt/mTOR signalling is central to the Notch1 signalling pathway, suggesting that targeting PI3K/Akt/mTOR with small molecule inhibitors would show great promise in treating osteosarcoma." (PMID 34495871, 2021).
osteosarcoma (continued). "Both osteosarcoma cell lines exhibited markedly enhanced Homer1 expression compared to primary osteoblasts, along with increased expression of CaSR, mTOR, the mTORC2 specific protein Rictor, but not the mTORC1 specific Raptor, and the effects were particularly pronounced in SAOS-2." (PMID 34204449, 2021). "The results showed that RAPA could not affect the apoptotic rate induced by miR-126 in U2OS cells, suggesting that the mTOR pathway is not involved in miR-126 promotion of apoptosis in osteosarcoma U2OS cells." (PMID 25510179, 2014). "Additionally, targeting the Ras/Akt/mTOR and Ras/ERK1/2/HIF-1α pathways with self-assembling nanoparticles encapsulating zoledronic acid (NZ) can simultaneously upregulate ABCA1 and downregulate ABCB1, thereby restoring drug sensitivity in doxorubicin-resistant osteosarcoma." (PMID 40283955, 2025). "It was suggested that arbutin could inhibit osteosarcoma cell proliferation, migration and invasion via miR-338-3pl MTHFD1L (methylenetetrahydrofolate dehydrogenase (NADP+ Dependent) 1 Like) and by inactivating the AKT (protein kinase B)/mTOR (mammalian target of rapamycin) signaling pathway." (PMID 36557918, 2022). "It should be noted that our findings stand somewhat in contrast to those of Akin and colleagues, who found that while NSC185058 treatment slowed growth in osteosarcoma, it did not appear to alter PI3K or mTOR activity." (PMID 38582781, 2024). "Although studies on the possible role of these enzymes in osteosarcoma are lacking, their effects suggest a tumor suppressor role for DEPTOR in osteosarcoma, as its upregulation should result in reduced mTOR pathway activity." (PMID 38534381, 2024). "It is also worth noting that although EFEMP2 overexpression activated the PI3K/AKT/mTOR pathway promoting EMT, it did not affect osteosarcoma cells in which STEAP2 or Akt was knocked down." (PMID 36316642, 2022). "TRIM22 inhibites osteosarcoma progression by promoting proteasomal degradation of NRF2 independent of KEAP1, thereby activating AMPK/mTOR/autophagy signaling that led to autophagic osteosarcoma cell death." (PMID 36261847, 2022). "A combination of palbociclib and a mammalian target of rapamycin (mTOR) inhibitor, everolimus, significantly inhibited, but did not regress, the PDOX growth of osteosarcoma." (PMID 36003796, 2022). "An osteosarcoma xenograft model showed that aloin inhibited osteosarcoma and mediated the PI3K/AKT/mTOR pathway in vivo, with no adverse reactions in major organs." (PMID 34819120, 2021). "With a lack of available clinical agents active in osteosarcoma, PI3K/mTOR inhibition represents a potential vulnerability in osteosarcoma that warrants clinical investigation." (PMID 27441088, 2016).
bladder cancer (328 papers, 2009 to 2026). "The AKT/mTOR pathway has been implicated in bladder cancer tumorigenesis, and previous studies in other types of cancers have shown that amiodarone downregulates AKT activity." (PMID 40353763, 2025). "The AKT/mTOR signaling pathway is crucial for cell survival and growth and has been implicated in bladder cancer tumorigenesis." (PMID 40353763, 2025). "Bladder cancer (BC) has some frequent mTOR alterations, with the most common mutations occurring in the TSC1 and PIK3CA genes, as well as copy number alterations affecting the PIK3CA gene." (PMID 39258533, 2025). "Using this strategy for high-risk NMIBC, we identified three mTOR inhibitors among the compounds with a high score for reversing aggressive bladder cancer molecular signatures." (PMID 40353763, 2025). "Despite the increased activity of the mTOR pathway in bladder cancer, therapy based on mutational status with inhibitors of the mTOR signaling pathway have not necessarily proven successful in this disease." (PMID 35326708, 2022). "Then, GSEA of the KEGG results showed apparent enrichment of the terms bladder cancer, ubiquitin-mediated proteolysis, cell cycle, DNA replication, and mTOR signaling pathway in the high-risk group." (PMID 36110218, 2022). "Cross-talk between ROS and the PI3K/Akt/mTOR axis has meanwhile been confirmed by others as the main cause for apoptosis modulation in bladder cancer." (PMID 34073079, 2021). "The potential benefit of the mTOR-inhibitors, temsirolimus and everolimus, has been demonstrated only for a subset of bladder cancer patients, and use of these drugs has been associated with severe, not well-tolerated, adverse events." (PMID 32512849, 2020). "In particular, we focused on the effect of AZD5363 (an AKT inhibitor), AZD2014 (an mTOR inhibitor), and BEZ235 (a dual PI3K/mTOR inhibitor) alone or in combination on two bladder cancer cell lines differing in their mTOR mutation status." (PMID 32325639, 2020). "Previously, we showed that AMPK-mediated mTOR signaling inhibition induced aberrant ROS accumulation, causing defects in the oxidative machinery and mitochondrial membrane potential in lung and bladder cancer cells." (PMID 33302414, 2020). "In the present study, we selected two bladder cancer cell lines to compare the efficacy of mTOR inhibitors depending on the mTOR mutation status." (PMID 32325639, 2020). "The present findings reveal that chronic use of the mTOR inhibitor everolimus is associated with resistance development in bladder cancer cells, resulting in aggressive regrowth and tumor progression." (PMID 32512849, 2020). "Poor survival rate is major risk factor associated with mTOR signaling aberrations in bladder cancer." (PMID 33292283, 2020). "Sequencing the genome of one exceptional responder in a failed clinical trial of everolimus in bladder cancer, an inhibitor of the gene mTOR, identified a mutation of a key mTOR regulator, the TSC1 gene." (PMID 30084865, 2019). "Akt/mTOR-signaling has been associated with migration and invasion of bladder cancer cells, whereby Rictor seems particularly involved in cytoskeleton organization and cell polarity." (PMID 31167517, 2019). "These alterations in the mTOR pathway are reported to be associated with progression and mortality in bladder cancers (n = 887) and are valuable for prognosis." (PMID 30754640, 2019). "In the present study we investigated the impact of PI3K/AKT/mTOR gene polymorphisms on bladder cancer risk." (PMID 29383014, 2018). "Validation of the findings in larger sample sizes and different ethnicities would provide evidence for the role of variants of PI3K/AKT/mTOR pathway in bladder cancer development." (PMID 29383014, 2018). "Deregulation of the PI3K/Akt/mTOR pathway was associated with remarkable efficacy of mTOR inhibitors such as rapamycin or everolimus in bladder cancer cells in vitro and in xenograft models." (PMID 29454321, 2018).
bladder cancer (continued). "Pathway and interactome analysis predicted strong activation in muscle invasive bladder cancer of pathways associated with protein synthesis e.g. eIF2 and mTOR signalling." (PMID 28880921, 2017). "In a recent study, Raptor gene polymorphisms were associated with increased risk for bladder cancer; physical activity, energy balance and genetic variants in the mTOR pathway co-coordinately influenced bladder cancer risk." (PMID 28977864, 2017). "Pathway and interactome analysis predicted strong activation in muscle invasive bladder cancer of pathways associated with protein synthesis e.g. eIF2 and mTOR signaling." (PMID 29050215, 2017). "By contrast, in bladder cancer PTEN deficiency is associated with reduced sensitivity to mTOR inhibitor." (PMID 27374081, 2016). "Particularly, the PI3K/Akt/mTOR pathway was also found to be associated with a substantial number of bladder cancers." (PMID 26931119, 2016). "In particular, a subset of mTOR pathway alterations have been shown to occur in bladder cancer, such as mutations in PIK3CA gene, which culminates with increased mTOR signaling and bladder cancer cells resistance to apoptosis." (PMID 26569621, 2015). "Multiple studies demonstrate that the activation of the mTOR pathway could be imminent during the tumorigenesis process in bladder cancer and predisposes the development of the disease and unfavorable survival." (PMID 41179371, 2025). "However, the regulation of mTOR signaling in bladder cancer is complicated and the underlying mechanism remains elusive." (PMID 36085200, 2022). "In conclusion, our findings suggest that PIK3CA rs6443624, AKT1 rs2498801, AKT1 rs1130233, as well mTOR rs2295080 polymorphism may be related to bladder cancer development in a sample of Iranian population." (PMID 29383014, 2018). "Therefore, this case-control study was designed to assess the possible association between PIK3CA, AKT1 and mTOR polymorphisms and susceptibility to bladder cancer in an Iranian population." (PMID 29383014, 2018). "Overall, our data suggest that a comprehensive profiling, rather than solely mutational analysis, may predict response to PI3K/mTOR targeted therapies in bladder cancer." (PMID 27823983, 2016). "It is important to note that mTOR is strongly associated with EMT in bladder cancer." (PMID 26267811, 2015). "In our study, the addition of exogenous ATP alleviated MB-10-induced inactivation of Akt-mTOR cascade in priBlCa-1 cells, suggesting that reduction in ATP levels could be the primary mechanism underlying the inhibition of the Akt-mTOR cascade by MB-10 in bladder cancer cells." (PMID 38467612, 2024). "However, although mutation of HRAS as well as FGFR3 and PI3K/AKT/mTOR components are associated with development of noninvasive bladder cancer, it is unknown if the hyperplastic and/or transformed state depends upon maintenance of oncogene expression." (PMID 30670749, 2019). "Urothelial hyperplasia and early stage, noninvasive bladder cancer frequently exhibit mutations in the gene encoding fibroblast growth factor receptor 3 (FGFR3) as well as components of the phosphoinositide 2-kinase/AKT/mammalian target of rapamycin (PI3K/AKT/mTOR) pathway." (PMID 30670749, 2019). "Together, the results indicate that the mTOR–SREBP–DS2 axis plays a pivotal role in ferroptosis resistance in bladder cancer." (PMID 40682485, 2025). "Together with our discovery of TAK‐228‐induced EGF and IFNβ contributing to PD‐L1 upregulation in bladder cancer cells adds to understanding multiple mechanisms modulating PD‐L1 during mTOR inhibition by TAK‐228." (PMID 39258533, 2025).